HPSE (heparanase)
Diseases named in the same sentence as HPSE in open-access papers (continued):
Sharing a sentence is not in itself a finding about the gene and the disease.
focal and segmental glomerulosclerosis (2 papers, 2017 to 2018). "Moreover, eNOS prevents heparanase induction and the development of proteinuria in a model of focal segmental glomerulosclerosis." (PMID 30546836, 2018).
Hodgkins lymphoma (2 papers, 2015). A heterogeneous group of malignant lymphoid neoplasms of B-cell origin characterized histologically by the presence of Hodgkin and Reed-Sternberg (HRS) cells in the vast majority of cases. "High levels of heparanase have also been reported in the plasma of Hodgkin's lymphoma (HL) patients and it can be used to evaluate treatment response." (PMID 26293675, 2015).
Hypertension (2 papers, 2017 to 2020). The presence of chronic increased pressure in the systemic arterial system. "Taken together, these studies illustrate a process whereby an ischemic placenta could upregulate heparanase, increase heparan sulfate cleavage, and release vast quantities of previously bound sFlt-1, leading to hypertension and other manifestations." (PMID 32600401, 2020).
Hypoalbuminemia (2 papers, 2012 to 2021). The concentration of albumin in the blood circulation is below the lower limit of normal. "In transplanted patients, urine heparanase/creatinine was significantly associated with urine protein/creatinine (p<0.006), and significantly inversely associated with serum albumin (p<0.02), suggesting a causal effect of heparanase in the development of proteinuria and hypoalbuminemia." (PMID 23028487, 2012). "Similarly, patients who displayed hypoalbuminemia tended to have increased HPSE activity." (PMID 34987504, 2021).
Insulin resistance (2 papers, 2019). Increased resistance towards insulin, that is, diminished effectiveness of insulin in reducing blood glucose levels. "Insulin and high glucose in obese and insulin resistance conditions might induce the heparanase upregulation." (PMID 31890010, 2019).
Lewis Lung carcinoma (2 papers, 2017 to 2018). "A similar phenotype was observed in a model of Lewis lung carcinoma cells implanted in heparanase-knockout vs wild type mice." (PMID 29721203, 2018).
liver disease (2 papers, 2017 to 2022). "The fact that these results were observed in patients with both autoimmune liver disease and viral hepatitis suggests that the pathological events that are at the basis of HPSE up-regulation are probably the same independently of the etiology of liver disease." (PMID 29097791, 2017).
lung adenocarcinoma (2 papers, 2018 to 2021). A carcinoma that arises from the lung and is characterized by the presence of malignant glandular epithelial cells. "Overexpression of heparanase in HCC-827 lung adenocarcinoma cells resulted in a markedly increased heparanase enzymatic activity (release of heparan sulfate degradation fragments from a naturally produced ECM) and cellular invasion through a reconstituted ECM (Matrigel)." (PMID 29721203, 2018).
lung injury (2 papers, 2019 to 2023). "Furthermore, endothelial glycocalyx degradation via heparanase activation has already been demonstrated in the pathophysiological process of acute lung injury, in which an aberrant epithelial heparanase expression might be assumable as well." (PMID 37386200, 2023).
malaria (2 papers, 2019 to 2021). Malaria is a serious and sometimes fatal disease caused by a parasite that commonly infects a certain type of mosquito which feeds on humans. "Inflammation associated with malaria triggers increased heparanase activity that degrades the heparan sulfate on the membrane‐bound syndecan‐1." (PMID 30919596, 2019). "The findings in our study suggest that in addition to the role of angiopoietin-2 in mediating glycocalxy breakdown in malaria, agents that increase heparanase expression such as ADMA and OPG may also contribute." (PMID 33963210, 2021).
metastatic melanoma (2 papers, 2016 to 2024). A melanoma that has spread from its primary site to another anatomic site. "Heparanase has previously been shown to be overexpressed in 88% of metastatic melanoma samples, with high expression associated with decreased survival in a subset of 46/69 stage IVc patients." (PMID 39594665, 2024). "The aim of the current study was to examine the expression and significance of heparanase in metastatic melanoma." (PMID 27732945, 2016). "To that end, we examined heparanase expression in metastatic melanoma and its correlation with clinical parameters." (PMID 27732945, 2016). "Heparanase inhibition represents a promising area for the control of metastatic melanoma." (PMID 39594665, 2024). "For the entire cohort of metastatic melanoma patients, no apparent correlation was found between heparanase staining intensity and survival." (PMID 27732945, 2016).
minimal change disease (2 papers, 2012 to 2017). "Other authors indicate that urinary heparanase excretion is increased in the course of membranous glomerulopathy, focal, and segmental glomerulosclerosis, and minimal change disease." (PMID 27091112, 2017).
multiple sclerosis (2 papers, 2014 to 2024). A progressive autoimmune disorder affecting the central nervous system resulting in demyelination. "In addition, HPSE has been implicated in central nervous system inflammatory disorders such as multiple sclerosis." (PMID 25295599, 2014).
phaeochromocytoma (2 papers, 2019 to 2022). "In this context, an interaction with heparanase-1 is possible because this protein is also detected in pelvic ganglia and, at least in rat phaeochromocytoma cells, heparanase-1 modulates neuritogenesis." (PMID 35812751, 2022). "Heparanase, the enzyme inhibited by heparanase 2,11 modulates neurite outgrowth from pheochromocytoma cells, and heparanase protects against axonal degeneration after sciatic nerve injury." (PMID 30885509, 2019).
Pleural effusion (2 papers, 2018 to 2021). The presence of an excessive amount of fluid in the pleural cavity. "In our cohort, patients who presented with fluid accumulation (n=16), either ascites or pleural effusion, showed significantly higher plasma heparanase activity." (PMID 34987504, 2021). "Clinically, heparanase levels in patients’ pleural effusions could distinguish between malignant and benign effusions, and heparanase H-score (immunostaining of tumor specimens) above 90 was associated with reduced patient survival." (PMID 30627323, 2018).
preeclampsia (2 papers, 2018 to 2022). Preeclampsia is a hypertensive disorder of pregnancy that is characterized by new-onset hypertension with proteinuria presenting after 20 weeks of gestation, and depending on mild or severe forms may initially present with severe headache, visual disturbances, and hyperreflexia. "Heparanase, the only endo-β-glucuronidase in mammalian cells, has been shown to be abnormally expressed in the placenta of preeclampsia patients in our previous study." (PMID 29849826, 2018). "Our study suggests that heparanase can be a potential predictive biomarker for preeclampsia at an early stage of pregnancy and represents a promising therapeutic target for the treatment of preeclampsia." (PMID 29849826, 2018). "When heparanase expression was evaluated in placental tissue from nine preeclamptic patients and three healthy controls at term, it was found thst it is overexpressed in preeclamptic placentas compared to controls, confirming its feasible contribution to the development of preeclampsia." (PMID 36613805, 2022).
renal carcinoma (2 papers, 2015 to 2022). A carcinoma arising from the epithelium of the renal parenchyma or the renal pelvis. "The t5 alternate form of heparanase found in renal cancers was not increased by FGF23." (PMID 25944690, 2015). "The short, alternative t5 form of heparanase expressed by renal cancers was not increased by FGF23." (PMID 25944690, 2015).
squamous cell carcinoma (2 papers, 2019 to 2022). A carcinoma arising from squamous epithelial cells. "In squamous cell carcinoma of the head and neck, nuclear localization of heparanase predicted a good outcome, whereas cytoplasmic heparanase correlated with a poor prognosis." (PMID 31850210, 2019).
thyroid carcinoma (2 papers, 2015 to 2021). "This study shows, for the first time, a distinct profile of HPSE expression in thyroid carcinoma suggesting its role in carcinogenesis." (PMID 26488476, 2015). "Therefore, the aim of the present study was to study the role of heparanase and heparanase-2 in thyroid carcinogenesis, in an effort to contribute to distinguishing between differentiated thyroid carcinoma and benign lesions." (PMID 26488476, 2015).
AA amyloidosis (1 paper, 2012). Secondary amyloidosis is a form of amyloidosis, that complicates chronic inflammatory disorders (mainly rheumatoid arthritis) and is characterized by the aggregation and deposition of amyloid fibrils composed of serum amyloid A protein, an acute phase reactant. "The results indicate that both heparanase and MMPs play important parts in the pathological process of AA amyloidosis." (PMID 22808071, 2012). "Our early in vivo studies reveal that overexpressing heparanase, an endo-glucuronidase specifically cleaves HS and heparin, attenuated the mice to AA amyloidosis induced by injection of AEF, providing a direct evidence for a critical role of HS in SAA deposition." (PMID 22808071, 2012). "Thus, it should be of interest in clinic to examine the patients who developed AA amyloidosis for the expression of MMPs and heparanase." (PMID 22808071, 2012). "As heparanase modulates, by degradation, the structure and, accordingly, the functions of HS, it is anticipated that elimination of heparanase may have an impact on AA amyloidosis." (PMID 22808071, 2012). "In this study, we assumed that the non-degraded long HS chains in heparanase deficient mice (Hpa-KO) might promote AA amyloidosis." (PMID 22808071, 2012).
acute cystitis (1 paper, 2025). An acute infection of the bladder. "This shows that the HPSE inhibitor OGT2115 was able to ameliorate the urinary symptoms of increased voiding frequency and decreased urine output in mice with CYP-induced acute cystitis and reduce lower abdominal sensitivity." (PMID 40408331, 2025).
and neck cancer (1 paper, 2021). "In order to investigate whether the HPSE expression correlates with prognosis in bladder, breast, gastric, lung, colorectal, head, and neck cancer patients, we used the PrognoScan, GEPIA, and Kaplan–Meier plotter databases to evaluate the impact of HPSE expression on survival." (PMID 34461608, 2021).
autoimmune disease (1 paper, 2024). A disorder resulting from loss of function or tissue destruction of an organ or multiple organs, arising from humoral or cellular immune responses of the individual to their own tissue constituents. "Finally, to explore the translational potential of our findings, we assessed the impact of HPSE overexpression on the stability and function of chimeric antigen receptors (CAR) Treg stability and function, which show promise for the treatment of autoimmune diseases, such as MS38,39." (PMID 38378682, 2024).
autoimmune liver disease (1 paper, 2017). "As observed in patients with autoimmune liver diseases, F4 fibrotic patients affected by hepatitis C (HCV) and hepatitis B (HBV) also had basal plasma HPSE activity." (PMID 29097791, 2017).
choriocarcinoma (1 paper, 2018). An aggressive malignant tumor arising from trophoblastic cells. "When HPSE was overexpressed, HTR8/SVneo cells exhibited enhanced proliferation and invasion that was characteristically similar to choriocarcinoma (CCA)." (PMID 29849826, 2018).
chronic gastritis (1 paper, 2021). Inflammation of the stomach that is chronic in nature. "To investigate the role of heparanase in chronic gastritis, we infected Hpa-KO and Wild Type (WT) C57BL/6 mice with H. pylori, and the degree of inflammation in the gastric mucosa was examined after 8 weeks." (PMID 34220822, 2021). "Compared to normal gastric tissue, heparanase was overexpressed in H. pylori-infected chronic gastritis and intestinal metaplasia, indicating that high expression of heparanase is involved in bacteria-induced inflammation." (PMID 34220822, 2021). "Heparanase is highly expressed in chronic gastritis with H. pylori infection, but the source of heparanase in gastritis tissue is still unclear." (PMID 34220822, 2021). "Compared to normal gastric tissue, heparanase staining was readily detected in chronic gastritis, gastric mucosa and chronic atrophic gastric mucosa." (PMID 34220822, 2021). "Collectively, both the qPCR and flow cytometry analyses imply that heparanase facilitates the infiltration of macrophages in H. pylori-infected chronic gastritis." (PMID 34220822, 2021). "Our results indicate that heparanase regulates primarily the recruitment and accumulation of macrophages in H. pylori-induced chronic gastritis tissue, in agreement with previous studies on the impact of heparanase on macrophage recruitment and activation in cancer and inflammation." (PMID 34220822, 2021). "Importantly, a positive correlation between expression of heparanase and colonization of H. pylori was found in human chronic gastritis, further confirming the results of our mouse model." (PMID 34220822, 2021). "Here, we examined the involvement of heparanase in H. pylori-induced gastritis, which, test gastritis tissues and established a mouse model of H. pylori-infected chronic gastritis Expression and tissue localization of heparanase were illustrated by immunofluorescence and immunohistochemistry." (PMID 34220822, 2021). "Likewise, our results indicate that the main cellular source of heparanase in H. pylori-induced chronic gastritis are epithelial cells of the gastric mucosa, yet overexpression of heparanase in macrophages was also observed." (PMID 34220822, 2021). "The role of heparanase in chronic gastritis caused by H. pylori has not yet been explored." (PMID 34220822, 2021). "Since heparanase facilitated the infiltration of macrophages in H. pylori-infected chronic gastritis, we stained H. pylori-infected human gastritis tissue for CD68 and heparanase." (PMID 34220822, 2021). "Heparanase is highly expressed in a variety of inflammatory conditions and diseases, but its role in chronic gastritis has not been sufficiently explored." (PMID 34220822, 2021). "While the participation of heparanase in immunocyte chemotaxis, recruitment, extravasation, migration and accumulation in target inflammatory sites, is well documented, its impact on immunocytes in H. pylori-induced chronic gastritis has not been analyzed." (PMID 34220822, 2021).
Cirrhosis (1 paper, 2019). A chronic disorder of the liver in which liver tissue becomes scarred and is partially replaced by regenerative nodules and fibrotic tissue resulting in loss of liver function. "Because 90% of HCC cases have a natural history of unresolved inflammation and severe fibrosis (or cirrhosis), we then examined the fibrosis marker genes, including collagen type I alpha 1 (cola1a1), connective tissue growth factor (ctgfa), and heparanase (hpse) in the AURKA transgenic fish." (PMID 31269749, 2019).
clear cell renal cell cancer (1 paper, 2011). "Tumor angiogenesis is important in the progression of malignancies, and heparanase plays an important role in sustaining the pathology of clear cell renal cell cancer (ccRCC)." (PMID 22133010, 2011).
cystinosis (1 paper, 2025). Cystinosis is a metabolic disease characterized by an accumulation of cystine inside the lysosomes, causing damage in different organs and tissues, particularly in the kidneys and eyes. "The expression of SDC-1 and SDC-4 in the bladders of CYP-induced cystinosis mice was low and not significantly different, and the expression of SDC-2 and HPSE was significantly elevated in the CYP group." (PMID 40408331, 2025).
cystitis (1 paper, 2025). Inflammation of the urinary bladder. "Improvement of lower urinary tract symptoms and restoration of the uroepithelial cell anti-leakage barrier in mice with CYP-induced cystitis after treatment with the HPSE inhibitor OGT2115 and inhibited the development of EMT." (PMID 40408331, 2025). "Additionally, we used the HPSE inhibitor OGT2115 to treat CYP-induced cystitis in mice and validate phenotypic changes." (PMID 40408331, 2025).
diabetic neuropathy (1 paper, 2018). A chronic, pathological complication associated with diabetes mellitus, where nerve damages are incurred due to diabetic microvascular injury involving small blood vessels that supply these nerves, resulting in peripheral and/or autonomic nerve dysfunction. "All these researches suggests that NO-heparanase signaling is a crucial target for the treatment of GECs barrier damage in diabetic neuropathy." (PMID 30319431, 2018).
endometrial carcinoma (1 paper, 2020). A malignant tumor arising from the epithelium that lines the cavity of the uterine body. "In EC, previous studies showed higher HPSE expression in endometrial carcinoma of grade 2 + 3, advanced FIGO stage and carcinoma with deep myometrial invasion, positive lymph node, lymphvascular space involvement." (PMID 32869952, 2020). "Previous studies showed high HPSE expression in nearly all human carcinomas examined including renal, thyroid, hepatocellular (Chen, Dang, Luo, Feng, & Tang, 2008), lung, breast, ovarian, and endometrial cancer." (PMID 32869952, 2020). "HPSE SNPs of rs4693608 (G > A) and rs4364254 (C > T) were analyzed using polymerase chain reaction‐restriction fragment length polymorphism (PCR‐RFLP) assay in 270 endometrial cancer patients and 320 healthy controls." (PMID 32869952, 2020).
endometriosis (1 paper, 2024). The growth of functional endometrial tissue in anatomic sites outside the uterine body. "Existing studies have indicated that ACE, HPSE, HYAL2, LMAN2, and SULF2 are related to endometriosis." (PMID 39062484, 2024).
esophageal tumor (1 paper, 2022). "Thus, low HPSE expression might enhance the ability of growth factors to bind to esophageal tumor cells and confer worse prognosis." (PMID 35840985, 2022).
follicular adenomas (1 paper, 2015). "The most relevant data demonstrated an overexpression of HPSE in papillary thyroid carcinoma compared to follicular adenomas and thyroid neoplastic cell lines." (PMID 26488476, 2015).
gallbladder carcinoma (1 paper, 2022). "After years of research on gallbladder carcinoma, our group found that the invasion and migration of gallbladder cancer cells significantly increased after overexpressing heparanase." (PMID 35976177, 2022). "The high expression of heparanase in gallbladder cancer cells could significantly down‐regulate the expression of syndecan‐1." (PMID 35976177, 2022).
gastric signet ring cell adenocarcinoma (1 paper, 2018). "High expression (p = 0.0327) of HPSE protein was found in the ascitic samples of primary gastric signet ring cell adenocarcinoma (SRCA) as compared to gastric non-SRCA and colic cancer by ELISA." (PMID 30333909, 2018).